USP7 (ubiquitin specific peptidase 7)
Diseases named in the same sentence as USP7 in open-access papers (continued):
Sharing a sentence is not in itself a finding about the gene and the disease.
cancer (continued). "USP7 plays multi-dimensional roles in various cancers, including prostate cancer, lung cancer, brain cancer, colon cancer, breast cancer, epithelial ovarian carcinoma, liver cancer, and leukemia." (PMID 32781716, 2020). "In recent years, due to the critical role of USP7, its inhibitors have been interested for cancer treatment." (PMID 32002017, 2020). "The multiple roles of USP7 have been studied in various carcinomas, including prostate, lung, breast, ovary, brain, and colon." (PMID 33207738, 2020). "USP7 is the first USP recognized as one of the cancer therapeutic DUB targets due to its important roles in tumorigenesis, cancer metastasis and HIV progression." (PMID 31730000, 2019). "It’s worth thinking about USP7 inhibitors in combination with immunotherapy will be applied to cancer therapy so that the antitumor effect can be promoted." (PMID 31114498, 2019). "USP7 has been identified as an oncogene with an important role in carcinogenesis and therapeutic resistance in a variety of cancer types." (PMID 31730000, 2019). "A major part of cancer promoting genes were embryonic neural specific, including genes for deubiquitases USP7 and USP39." (PMID 31130994, 2019). "Through its deubiquitination activity, USP7 regulates the stability, function, or localization of its substrates, and plays important roles in cancer development, cell signaling, DNA damage repair, epigenetic regulation, and immune responses (reviewed by21)." (PMID 31519875, 2019). "We also show that EZH2 plays a key role in the maintenance of stability of its interaction partners, via interaction with deubiquitase USP7, so as to maintain a network promoting cancer initiation and progression." (PMID 31130994, 2019). "USP7 is highly expressed in a wide variety of cancers and affects the progression of cancer diseases." (PMID 31114498, 2019). "USP7 has been reported to promote the stability of quite a few proteins, especially during cancer initiation and progression." (PMID 31130994, 2019). "The deubiquitinase USP7 has been identified as an oncogene with key roles in tumorigenesis and therapeutic resistance for a series of cancer types." (PMID 31730000, 2019). "USP7 is a critical component in Ubiquitin proteasome system and its role is well established in tumorigenesis and cancer progression, makes it a target of immense interest." (PMID 30344943, 2018). "Many studies have revealed that selective inhibition of USP7 can be an efficient mechanism to arrest cancer." (PMID 30344943, 2018).
cancer (continued). "Considering the crucial role of USP7 in cancer development, much attention has been paid to developing USP7 inhibitors for cancer therapy." (PMID 30370059, 2018). "Similar to other cancers, USP7 is overexpressed in T-ALL, suggesting a possible role in T-ALL pathogenesis." (PMID 30370059, 2018). "To assess the USP7 expression in T-ALL, we first analyzed the transcript expression in a wide array of human cancer cell lines and discovered that USP7 was highly expressed in T-ALL." (PMID 30370059, 2018). "The ubiquitin specific protease, USP7, regulates multiple cellular pathways relevant for cancer through its ability to bind and sometimes stabilize specific target proteins through deubiquitylation." (PMID 30367141, 2018). "In keeping with the roles of USP7 in regulating several cancer-related pathways, upregulation of USP7 in several cancers has been shown to promote oncogenesis, identifying USP7 as an attractive target for cancer therapy." (PMID 30367141, 2018). "Another study identified a small molecule, HBX 41,108, a cyano-indenopyrazine derivative that inhibits USP7 activity in a reversible manner both in vitro and in cancer cells with an IC50 value in the submicromolar range." (PMID 29479529, 2018). "Recently a few inhibitors have been developed to specifically target USP7 with promising results in different cancer models." (PMID 28418900, 2017). "This further implies a promising safe and efficient therapeutic window of USP7 inhibitors for cancer treatment." (PMID 29045831, 2017). "Deubiquitinating enzyme USP7 has been involved in the pathogenesis and progression of several cancers." (PMID 27780924, 2016). "Among the inferred targets are tousled-like kinase 2 (TLK2) and the deubiquitinating enzyme ubiquitin-specific-processing protease 7 (USP7) whose overexpression correlates with poor survival in cancers." (PMID 26427375, 2015). "A precise understanding of USP7 regulation is necessary to target USP7 for the development of cancer therapeutics." (PMID 26046769, 2015). "We wonder if the use of specific USP7 inhibitors would enhance CCDC6 turnover in order to sensitize cancer cells to the PARP inhibitors in combination with standard chemotherapies." (PMID 25885523, 2015). "These USP7 substrate proteins play critical roles in pathways that are often dysregulated in cancer highlighting the importance of investigating USP7 as a therapeutic target in cancers involving these proteins." (PMID 25605410, 2015). "We therefore analyzed the relationship between the USP7 and epithelial and mesenchymal markers expression in cancer tissues and cells." (PMID 25519684, 2015). "This USP7-dependent deubiquitination and removal of PTEN from the nucleus is associated with many cancers." (PMID 25605410, 2015). "Despite the fact that USP7 has emerged as a drug target for cancer therapy, structural details of USP7 regulation and the molecular mechanism of interaction at its CTD have remained elusive." (PMID 26046769, 2015). "Multivariate analysis showed USP7 overexpression was an independent prognostic marker for these cancers." (PMID 25519684, 2015).
cancer (continued). "To investigate the impact of USP7 on cancer cell invasiveness, we used transwell assays to study the different invasive abilities between H460-shUSP7 and H460-control cells." (PMID 25519684, 2015). "Firstly, we found that the high level of USP7 is more often with the low expression of E-cadherin in cancer tissues." (PMID 25519684, 2015). "The opposing roles played by USP7 and Mdm2 is critical for maintaining the level of Daxx in the cancer cells." (PMID 25121098, 2014). "USP7, a deubiquitylating enzyme hydrolyzing the isopeptide bond at the C-terminus of ubiquitin, is an emerging cancer target." (PMID 24473167, 2014). "In case of Rb, USP7 shows a differential deubiquitination in normal and cancer (glioma) cells depending on the Mdm2 levels." (PMID 25121098, 2014). "Since USP7 is as yet the only DUB discovered to be directly connected to both cancer and infectious diseases, it is very enticing to find suitable inhibitors that can be used efficiently and specifically against USP7." (PMID 23555268, 2013). "USP7 is also considered to be a therapeutic target for cancer therapy due to its broad role in genomic stability." (PMID 23209443, 2012). "This review summarizes current insights into USP7 structure and substrate networks, highlights its multifaceted roles in tumor immunity and metabolism, and discusses the therapeutic potential and translational challenges of targeting USP7 in cancer." (PMID 42245660, 2026). "As previously discussed, USP7 can play several roles in cancer progression and metastasis, acting either as an oncogenic protein or tumor suppressor based on the targets involved and the cancer type." (PMID 41157055, 2025). "According to a meta-analysis, which had a total of 1192 patients and assessed five types of cancer, the high-expression of USP7 may promote the progression of epithelial ovarian cancer (EOC) and predict unfavorable prognosis of EOC patients." (PMID 40568598, 2025). "Notably, the PROTAC U7D-1 was shown to selectively degrade USP7, effectively inhibiting cancer cell growth." (PMID 40607253, 2025). "Given the recent study of USP7 as a deubiquitinating enzyme of HPV16 E7 and the promise shown by the highly specific USP7 inhibitors in in vivo models, these USP7 inhibitors could have therapeutic potential in HPV+ cancers." (PMID 40011575, 2025). "In the next paragraphs, the major USP7 targets involved in cancer development will be discussed." (PMID 41157055, 2025). "The results indicate that USP7 might influence cancer cell stemness by potentially altering the expression of stemness markers like CD44, CD133, and Nanog, known for their link to the stem‐like traits of cancer cells." (PMID 40078091, 2025). "Among deubiquitinating enzymes, USP7 is the most widely studied in the context of cancer." (PMID 40247205, 2025). "Comparison of the functions of DACH1 and USP7 with previous studies not only revealed their unique roles in CRC but also highlighted the potential of targeting their post-translational modifications for cancer therapy." (PMID 40389405, 2025).
cancer (continued). "Consequently, USP7 represents a relevant pharmacological target for the treatment of various pathological disorders; in particular, its aberrant expression in many cancers has been widely studied to explore novel antitumor strategies." (PMID 41157055, 2025). "Among DUBs, USP7 stabilizes Mdm2 and represents an emerging target for cancer therapy." (PMID 40295432, 2025). "USP7 is an oncoprotein and is highly expressed in various human cancers." (PMID 37867415, 2024). "During chemotherapy, increased USP7 expression may engender drug resistance in cancer cells, thereby diminishing treatment efficacy." (PMID 39767641, 2024). "Second, USP7 may also influence cancer progression by modulating antiapoptotic pathways, including DNA damage signaling, starvation signaling, and oncogene activation signaling." (PMID 39767641, 2024). "To evaluate the role of USP7 on cancer cell growth under conditions where cancer cells are interacting with other TME components, we assessed the response of 3D tumour spheroids composed of cancer cells, fibroblasts and CD3/CD28‐activated immune cells to treatment with the USP7 inhibitor." (PMID 38602256, 2024). "Since we found that knockdown of USP7 by shRNA (shUSP7) led to a significant increase in the protein level of DICER, and DICER usually acts as a tumour suppressor according to several studies, it is possible that USP7 plays a role in cancer progression through DICER." (PMID 37867415, 2024). "In conclusion, the expression of USP7 has significant effects on cancer." (PMID 39767641, 2024). "USP7 can promote malignant behavior in cancer cells such as proliferation, migration, and invasion." (PMID 39767641, 2024). "As our understanding of USP7 continues to evolve, we expect to gain a more comprehensive understanding of its role in tumorigenesis and progression, thereby providing new perspectives and strategies for cancer therapy." (PMID 39767641, 2024). "In our study, we demonstrated that USP7 was overexpressed in colorectal stem-like cancer cells." (PMID 39346740, 2024). "This represents a function of USP7 that is unique to primary or cancer‐associated fibroblasts, and which is not observed in cancer cells or other cells present in the TME." (PMID 38602256, 2024). "USP7 inhibitors sensitize cancer cells to chemotherapy by decreasing SAMHD1." (PMID 38787520, 2024). "Previous studies have shown that USP7 plays different roles in the development of cancer." (PMID 38254206, 2024).
cancer (continued). "USP7 expression was significantly increased in three cancer types, including DLBCL." (PMID 39664521, 2024). "In the field of cancer research, the expression of USP7 has attracted great attention." (PMID 39767641, 2024). "Similarly, USP7 directly interacts with PD-L1 in GC, enhancing its stability and affecting cancer cell proliferation." (PMID 38474186, 2024). "USP7 plays a significant role in mediating cancer cell resistance to PARP inhibitors." (PMID 38702734, 2024). "Aberrant activation or overexpression of USP-7 might promote oncogenesis, making this protein a promising target for cancer treatment." (PMID 37298148, 2023). "Importantly, USP7 inhibitor sensitizes cancer cells to chemotherapy by decreasing SAMHD1, suggesting that SAMHD1 stabilization by USP7 promotes DNA damage repair to overcome oncogenic stress and affect chemotherapy sensitivity." (PMID 37081042, 2023). "We also found that USP7 activated these signalling molecules involved in cancer cell migration." (PMID 38082439, 2023). "Among them, USP7 has been thoroughly investigated in cancer pathophysiology." (PMID 36771100, 2023). "Taken together, these data suggest USP7 inhibition can synergize USP22-Ko effect in cancers." (PMID 37946202, 2023). "Therefore, combining PARP-inhibitor drugs with USP7 inhibitor besides the DNA damage inducer RRx-001, contributes to new immunotherapeutic strategy specific to cancer patients." (PMID 37658402, 2023). "Emerging studies have demonstrated that USP7 expression correlates with PD-L1 levels in cancer." (PMID 37415977, 2023). "These small-molecule degraders 24 efficiently induce apoptosis in USP7-dependent cancer cells." (PMID 36982263, 2023). "USP7 has both tumor suppressor and oncogenic roles in cancer development." (PMID 37605223, 2023). "Emerging evidence has suggested the implication of USP7 in initiation and development of cancer." (PMID 37081042, 2023). "A previous study employed the USP7-specific inhibitor P5091 to prevent cancer, however, the effect of this inhibitor on osteoclasts remains unclear." (PMID 37199589, 2023). "Taken together, the findings suggest that SAMHD1 may be a potential prognostic biomarker in the adjuvant and neoadjuvant setting, and that the combination of cytotoxic chemotherapy and USP7 inhibition might improve chemotherapy sensitivity in various cancers." (PMID 37081042, 2023). "Previous studies have reported that depletion of USP7 or USP47 inhibits cancer cell growth." (PMID 37740002, 2023). "Interestingly, very recent studies showed that MGA, L3MBTL2 and PCGF6 are also destabilized upon USP7 inactivation in human cancer cell lines, indicating conserved USP7 function through mammalian evolution." (PMID 36772830, 2023). "Interestingly, UbV7.2 was slowly released by the endosomes, inhibiting USP7 and resulting in cancer cell apoptosis." (PMID 37626927, 2023). "In addition, USP22-Ko cancer cells are more sensitive to a combination of cisplatin and USP7 inhibitor." (PMID 37946202, 2023). "USP7 inhibitors have been developed to perform anticancer ability in various cancer types." (PMID 37215134, 2023).